LAG3 (lymphocyte activating 3)
Diseases named in the same sentence as LAG3 in open-access papers (continued):
Sharing a sentence is not in itself a finding about the gene and the disease.
tumor (continued). "The expression of LAG3 was positively correlated with the infiltrating score of M1 macrophage and CD8+ T cells in all of tumor types we analyzed." (PMID 38041068, 2023). "Conversely, higher percentages of CD8+ CD127+ lymphocytes, CD8+ LAG3+ lymphocytes, CD8+ PD-1+ lymphocytes and IDO+ MDSCs were found in tumor samples." (PMID 36900156, 2023). "It has been proven in mouse cancer models that simultaneous blocking of LAG-3 and PD-1 co-expressed on CD4+ and CD8+ TILs can synergistically improve anti-tumor CD8+ T cell responses." (PMID 37841254, 2023). "LAG3 was the most promising immune checkpoint after PD-1 and CTLA-4, and higher LAG3 and FGL1 expression promoted tumor growth by suppressing the immune microenvironment." (PMID 36843949, 2023). "All immune checkpoints were significantly different between the normal and tumor groups (P < 0.05), in which PDCD1, CTLA4, and HAVCR2 were highly expressed in tumor tissues, while CD274, LAG3, and PDCD1LG2 were highly expressed in normal tissues." (PMID 37872211, 2023). "High LAG-3 and PD-1 levels significantly inhibit CD8+ T cell function, resulting in weakened ability to kill tumor cells." (PMID 37841254, 2023). "In contrast, in a paired longitudinal tumor tissue analysis performed on cHL, CD8‐positive T‐cell depletion and increased LAG‐3 expression were observed after anti‐PD‐1 therapy." (PMID 37326144, 2023). "Targeting some of these immune checkpoints as VISTA, LAG-3, Tim-3, and TIGIT led to additive effects and reactivation of tumor-specific T cells and clinical trials are still ongoing (NCT04475523, NCT02812875, (NCT0348936962–66." (PMID 37620318, 2023). "Of significance, the expression of coinhibitory receptors (PD1, KLRG1, LAG3, and TIM3) was considerably lower in CD8+ T cells retrieved from B16 Mgst1 KD tumor, and there was an increase in cytokine response (IFNγ and TNFα) along with Granzyme B." (PMID 37321450, 2023). "When comparing peripheral blood and tumor samples, significantly higher expression of CD127 and LAG3 within CD8+ lymphocytes, and increased IDO within MDSCs, were found in the tumors." (PMID 36900156, 2023). "The analyses of the co-expression of immunomodulatory molecules PD-1, PD-L1, ICOS, LAG3, TIM3, and IDO showed heterogeneous populations of immune and tumor cells." (PMID 38047086, 2023). "Positive TCF‐1 expression significantly correlated with advanced pathological stage, tumor grade, CD8+ TILs density, TIM‐3 expression, LAG‐3 expression, and PD‐1 expression." (PMID 37536668, 2023). "Accordingly, we aimed to evaluate the presence of CD45RO + and LAG3 + TILs in the CT and IM and their impacts on outcomes in CRC with particular focus on tumor location (right and left colon tumors)." (PMID 36765348, 2023). "In this study, the pre-treatment protein expression levels of CD8, PD-L1, LAG-3, and STAT-1 proteins within the HCC tumor microenvironment were determined using multiplex immunohistochemistry/immunofluorescence (mIHC/IF)." (PMID 37342338, 2023). "We found tumor-infiltrating T-cells (CD4, CD8), TAMs, MDSCs, and immune checkpoints including PD1, Lag3, and CTLA4 in C0321 tumors." (PMID 37901240, 2023). "In concordance with the expression patterns of immune checkpoint molecules, we demonstrated increased expression of immune suppressor markers such as FOXP3, Tim-3, and LAG3 on tumor CD8 T cells and CD11c+ cells with proximity to tumor tissue." (PMID 38044986, 2023). "As LAG-3, TIM3, BTLA, and TIGIT belong to the co-inhibitory receptors, which are known to impair anti-tumor immunity." (PMID 37946136, 2023). "In vitro activated PIT coexpressed PD-1, LAG-3 and TIGIT but were highly cytotoxic against autologous tumor and uniquely secreted cytokines and chemokines in the > 100 pM range." (PMID 37063842, 2023).
tumor (continued). "In mouse pre-clinical models and cancer patients, TIGIT expression on tumor-infiltrating CD8+ T cells often correlates with increased expression of other inhibitory receptors such as PD-1, LAG-3, TIM-3, and with decreased expression of DNAM-1." (PMID 37569880, 2023). "In a tumor model for local and distant tumors, AU-011 again synergized with ICI with the most efficient combination being AU-011 with PD-L1 and LAG-3, resulting in a 75% CR rate." (PMID 36997666, 2023). "Once bound to MHC II, the cytoplasmic domains of LAG-3 propagate inhibitory signals in CD4+ T lymphocytes, leading to its inactivation and the escape of tumor cells from undergoing immune cell-mediated apoptosis." (PMID 37345111, 2023). "We propose that pre-treatment levels of LAG-3+ and CD8+ cells in tumor tissue should be explored further to help identify HCC patients likely to benefit from immunotherapy using IHC-based techniques that are readily accessible during routine clinical care." (PMID 37342338, 2023). "Usually, exhaustion of tumor-specific CD8+ T cells leads to impairment of cytokine secretion and proliferation capacity, accompanied by PD1, TIM3, LAG3 and TIGIT overexpression." (PMID 37287907, 2023). "On exhausted tumour-specific CD8+ T cell subsets, TIGIT co-expresses with other inhibitory receptors, LAG3 and TIM-3." (PMID 37325585, 2023). "Treg and CD8+ T cells isolated from HCC TME expressed more PD-1, LAG-3 and TIM-3 than those isolated from non-tumor microenvironment (NTME) by proteomics and transcriptomic analysis, and showed T cell inhibition." (PMID 37304265, 2023). "LAG-3 is overexpressed on the membrane of tumor infiltrating lymphocytes and inhibition of LAG-3 results in a more efficient immune-mediated tumor clearance." (PMID 36674809, 2023). "In CRC patients LAG-3-positive Tregs produce IL-10 as wells as TGF-ß1 and are believed to be strongly activated and therefore directly involved in tumor immune evasion, due to direct contact inhibition of other T cells." (PMID 37958298, 2023). "The interaction between LAG3 on pDCs and MHC-II on tumor cells impairs IFN-α secretion and enhances IL-6 production, thus resulting in the formation of an immunosuppressive TME51." (PMID 37817484, 2023). "ICI therapy aims to overcome tumor immune escape through targeting immune inhibitory molecules (e.g., PD-1, PD-L1, LAG3, and CTLA4) expressed on the surfaces of tumor and immune cells." (PMID 37190216, 2023). "Several clinical trials have been established to evaluate anti-LAG-3, anti-TIM-3, or anti-TIGIT mAbs as different tumor therapies." (PMID 37670328, 2023). "In the case of a positive CIITA, a master regulator of MHC II, dual anti-LAG-3/PD-1 ICI attained profound antitumor impact and halted tumor growth in mice." (PMID 37345056, 2023). "Tumor cells overexpress FGL1 and PD-L1, which, respectively, bind to LAG-3 and PD-1 on T cells, forming important signaling pathways (FGL1/LAG-3 and PD-1/PD-L1) that negatively regulate immune responses." (PMID 37509610, 2023). "Immune checkpoint proteins, including Programmed Death 1 (PD-1) and its ligands PD-L1 and PD-L2, Lymphocyte Activation Gene 3 (LAG-3), CD200, Cytotoxic T Lymphocyte Activator 4 (CTLA-4), and CD47, are involved in tumor immunology and benefit tumor growth." (PMID 37626420, 2023). "Another functional ligand for LAG-3 is the fibrinogen-like protein 1 (FGL1), secreted by the liver and human tumor cells." (PMID 38162657, 2023). "ELOVL1 was positively correlated with PD-1 (PDCD1), CTLA4, LAG3, endothelial growth factors (VEGFs), and so on, which are the common immune checkpoints in the HCC tumor-immune microenvironment (TIME)." (PMID 35912257, 2022). "Positive correlation was also found between ZEB1 and TIM-3, as well as CD8 and the following markers: PD-1, PD-L1+ tumour cells, CD163, and LAG-3." (PMID 36358805, 2022).
tumor (continued). "We found that the high-risk group was significantly associated with higher expression level of immune checkpoints and immune inhibitory factors, including CCL2, CTLA4, CXCR4, IL6, LAG3, PDCD1, and TGFB1, indicating tumor immune evasion." (PMID 36092894, 2022). "B16-OVA tumors benefited from a synergistic effect, reaching 75% of tumor rejection, but higher levels of exhausted T-cells in LLC-OVA tumors co-expressing PD-1, LAG3 and TIM3 precluded similar levels of efficacy." (PMID 36300124, 2022). "These humanized monoclonal antibodies target inhibitory receptors (e.g., CTLA-4, PD-1, LAG-3, TIM-3) and ligands (PD-L1) expressed on T lymphocytes, antigen-presenting cells, and tumor cells and elicit an anti-tumor response by stimulating the immune system." (PMID 35528727, 2022). "Even when patients were stratified in quartiles depending on SMG1 expression in tumor samples, those with lower tumor levels of SMG1 displayed a CD8 phenotype with more abundance of cells expressing exhaustion markers (LAG3, PD-1, CTLA-4, TIM3, TOX)." (PMID 36443756, 2022). "LAG-3 is co-expressed with PD-1 on tumor-infiltrating CD8+ T cells, and the co-blockade of PD-1 and LAG-3 by antibodies elevated CD8+ T cells proliferation and cytokine production." (PMID 36077354, 2022). "LAG-3 and PD-1 have been shown to be co-expressed on TIL, and blockade of both regulators had synergistic effects on restoration of the anti-tumor CD8+ T cell response." (PMID 35053449, 2022). "Anti-LAG-3 mAb administration was found to increase the proliferation and effector function of CD8+ T cells and delay tumor growth in a prostate cancer mouse model." (PMID 35164813, 2022). "For this purpose, surface molecules expressed at much higher levels on Tregs than T cells are used as targets, such as CD25, CTLA-4, GITR, 4-1BB, OX-40, LAG3, TIGIT, CCR4, and CCR8; tumor burden control has also been observed." (PMID 36159809, 2022). "It is well known that in the field of tumour immunotherapy, five immune checkpoints, namely, PD-1, CTLA-4, Tim-3, LAG-3, and TIGIT, have inhibitory effects on T-cell proliferation." (PMID 36110204, 2022). "Expressions of CD274, CTLA4, LAG3, PDCD1, PDCD1LG2, and SIGLEC15 were shown to be significantly different between normal and tumor samples in immune checkpoint analysis." (PMID 36588699, 2022). "In previous pre-clinical murine cancer models, co-blockade of LAG3 and PDCD1 induced an up-regulation anti-tumor response." (PMID 34998385, 2022). "Critically, tumor-infiltrating TRM express immune checkpoint molecules including PD-1, CTLA-4, and LAG-3." (PMID 36466880, 2022). "In addition, LAG-3 and PD-1 may play a strong synergistic role in tumor immunosuppression." (PMID 35892835, 2022). "al, which proved that LAG-3 defines an active subset of CD4+CD25highFoxp3+ regulatory T cells whose frequency is increased in cancer patients and is spread at tumor sites." (PMID 36077354, 2022). "Low-level LAG-3 expression was noted in the initial activation of CD8+ T cells, and LAG-3 expression increased after tumour antigen stimulation." (PMID 35494015, 2022). "Many immune checkpoint molecules, including Programmed Death 1 (PD-1) and its ligands PD-L1 and PD-L2; Cytotoxic T Lymphocyte Activator 4 (CTLA-4); Lymphocyte Activation Gene 3 (LAG-3), and CD200, among others, involve in tumor immunology." (PMID 35922773, 2022). "A recent review stated that the main immune checkpoints on tumor-infiltrating and peripheral Tregs are CTLA-4, PD-1/PD-L1, LAG-3, TIM-3 and TIGIT." (PMID 36009853, 2022). "We detected the expression of PD-1, LAG-3, TIM-3, and TIGIT on TILs and on tumor cells among 174 DLBCL patients by IHC." (PMID 36561512, 2022). "CB213 showed superior activity vs. αPD1 antibody to induce ex vivo NSCLC patient T cell proliferation and to suppress tumour growth in a syngeneic mouse tumour model, for which both experimental systems possess PD1 and LAG3 suppressive components." (PMID 34969998, 2022).
tumor (continued). "SIGLEC15, PDCD1LG2 (PD-L2), TIGIT, PDCD1 (PD-1), HAVCR2 (TIM3), CTLA4, LAG3, and CD274 (PD-L1) are transcripts related to immunological checkpoints that have a function in tumor immune evasion." (PMID 36042287, 2022). "The surface expression of PD-1, LAG-3, and TIM-3 on CAR T cells after coculturing with tumor cells was determined via flow cytometry." (PMID 36457849, 2022). "LAG3 expressed on iTreg cells induces the production of TGF-β1 and IL-10, which contributes to tumor immune escape." (PMID 35958563, 2022). "The synergy between PD1 and LAG3 has been observed for anti-PD1 and anti-LAG3 antibody combinations in preclinical tumour models." (PMID 34969998, 2022). "PD-1, CTLA4, LAG3, and TIM-3 are four ICPs that are frequently examined in the clinic, and inhibitors targeting these factors have shown potent tumor-killing effects in a variety of tumors." (PMID 36203873, 2022). "LAG3/FGL1 axis has been identified as the major responsible for LAG3-induced immunity suppression and tumor growth enhancement." (PMID 36230819, 2022). "By attracting CD8+ TILs penetrating the tumor microenvironment (TME), LAG3 blockade combined with MWA increased the proliferation and activities of CD8+ T cells while reshaping myeloid cells." (PMID 36180876, 2022). "In accordance with our study, VISTA, LAG-3, and TIM-3 have been demonstrated to increase in the NSCLC tumor microenvironment rationalizing their potential as targets for NSCLC immunotherapy." (PMID 35493461, 2022). "Abundant studies have suggested that Foxp3 regulates the expression of several genes (CTLA-4, PD-1, LAG-3, TIM-3, TIGIT, TNFR2) involved in carcinogenesis to utilize its tumor suppressor function through knockout models." (PMID 36009853, 2022). "In the MC38 mouse tumor model, dual PD-1/TIM-3 blockade increases the expression of LAG-3 in T cells, and LAG-3 expression confers resistance to αPD-1/αTIM-3 treatment." (PMID 36605214, 2022). "To validate these findings in vivo, we evaluated the expression levels of CD80, VISTA, LAG-3, SIRP-α and TIM-3 on freshly isolated Ly6C+ monocytes, derived from healthy, Ctrl or anti-PD-L1 mAb treated tumor-bearing mice." (PMID 35493461, 2022). "In TILs, the positive rates of PD-1, LAG-3, TIM-3 and TIGIT were 79.3%, 78.8%, 62.7% and 69.5%, respectively.TIM-3 and TIGIT were expressed in 44.8% and 45.4% of tumor cells." (PMID 36561512, 2022). "Immune checkpoint molecules, such as PD-1, PD-L1, HAVCR2, LAG3, and CTLA-4, play an important role in tumor immune evasion." (PMID 36186792, 2022). "Subclusters with Entpd1 expression were assigned as tumor-specific T cells, including Treg (CD4+Foxp3+), CD8+ effector (Gzmb+Prf1+Ifng+), CD8+ effector memory (Cd44+Cd69+), CD8+ exhausted subclusters (Pdcd1+Lag3+Tigit+Havcr2+)." (PMID 36209176, 2022). "At the same time, in order to investigate the relationship between type and immune checkpoints, we selected genes related to tumor immune checkpoints: PD-L1, CTLA4, LAG3, PDCD1, PDCD1LG2, and TIGIT." (PMID 36105091, 2022). "IL-10 produced by MDSCs induce increased expression of lymphocyte activation gene 3 (LAG3) and the consequent decreased IL-2, IL-12, and IFNγ secretion by T cells, which hampered their proliferation and anti-tumor activity." (PMID 35757002, 2022). "Considering the important role of immune checkpoint molecules such as PD-1, PD-L1, LAG3 and CTLA-4 in tumor immune microenvironment, the expression levels of these molecules were explored between two groups." (PMID 36505846, 2022). "The selective binding of CB213 towards cells expressing both LAG3 and PD1 is designed to target the most dysfunctional tumour-specific T cells to reinvigorate T cell activity." (PMID 34969998, 2022). "LAG-3 knockout CAR-T cells maintained their antigen-specific cytokine release and anti-tumor potency in vitro and in vivo." (PMID 36077354, 2022).
tumor (continued). "It is with hope that an increased number of immune checkpoints (such as CTLA-4, PD-1, LAG-3, TIM-3, and TIGIT) be documented, although some tumor patients show immunotherapy tolerance." (PMID 35392063, 2022). "Studies on murine models showed that dual blockade of LAG-3 and PD-1 improved anti-tumor immune response by increasing CD8+ tumor-infiltrating cells in the TME and decreasing Treg cells." (PMID 36551630, 2022). "Altered-immunosuppressed tumor shows an intermediate degree of T cell and CTL infiltration and immunoscore, T cell checkpoints (PD-1, CTLA-4, TIM3, and LAG3), immune suppressive cells (MDSC and Treg), and inhibitory cytokines (TGF-, IL-10 and VEGF)." (PMID 36293435, 2022). "COL4A1 expression was also significantly correlated with the expression levels of T cell exhaustion marker genes such as PDCD1, CTLA4, LAG3, and HAVCR2 in all the four tumor types with only two exceptions (CTLA4 in SKCM and LAG3 in STAD)." (PMID 35455650, 2022). "This simultaneous genetic ablation of PD-1, LAG-3 and TIM-3 in CD8 T cells delayed tumor growth and improved survival." (PMID 36077354, 2022). "Immune checkpoints, including PD-L1/PD-1, CTLA4, lymphocyte activation gene 3 (LAG-3), IDO1 and galectin-9/TIM-3, which is the main mechanism of tumor immune escape via inhibiting the activation of effector T lymphocytes (Han, Liu and Li 2020)." (PMID 36313280, 2022). "Research found that combining select therapies with IDO1, LAG-3, and TIM-3 blockade tend to benefit against tumor growth." (PMID 36060266, 2022). "The FGL-1/LAG3 interaction appears to be an important, MHCII-independent, alternative mechanism for tumor evasion from immune defenses." (PMID 36140182, 2022). "MC38 tumors were unaffected by LAG3 blockade alone, whereas tumors in either the MWA group or MWA combined with LAG3 blockade group showed significantly delayed tumor outgrowth." (PMID 36180876, 2022). "The expression of CD274, CTLA4, LAG3, PDCD1, PDCD1LG2 and SIGLEC15 was significantly different between adjacent normal tissues and tumor tissues." (PMID 36588699, 2022). "We found that higher levels of tumour-infiltrating T cell subsets, including CD8+PD-1+LAG-3+TIM-3+, CD4+FoxP3+CTLA-4+ T and CD68+STING+ cells, were associated with inferior overall survival (OS) in 80 patients." (PMID 35982052, 2022). "In the 30 tumor types, PTBP1 expression had the most prevalent positive correlation with LAG3 and PD-1 expression." (PMID 36203873, 2022). "Dual blockade of LAG-3 and PD-1 also increased the number of tumor-infiltrating CD8+ T cells and reduced Tregs, thereby synergistically enhancing anti-tumor immunity." (PMID 36532071, 2022). "Patients with T2 tumors were more likely to have increased expression of PD-1, LAG-3, and TIGIT on tumor-infiltrating CD8+ cytotoxic T cells than those with T1 tumors." (PMID 36271406, 2022). "Tissue microarrays were evaluated for tumor-infiltrating lymphocytes (TILs) assessed morphologically on hematoxylin and eosin-stained slides, and by immunohistochemistry for CD8, FOXP3, LAG-3, PD-1 and PD-L1." (PMID 35954471, 2022). "CTLA-4, LAG-3, Tim-3, and PD-1 receptors are transiently expressed following TCR activation and bind to ligands expressed at the surface of tumor cells and of some immune cells (DCs, monocytes, B lymphocytes)." (PMID 35454873, 2022). "Immune checkpoint (ICP) inhibitors, including PD-1, CTLA4, LAG3, and TIM-3, have potent tumor suppressor effects and can interfere with immune escape; these inhibitors are currently the first-line treatment options for multiple malignancies." (PMID 36203873, 2022). "In addition, BMMC from MM patients (N = 5) treated with anti-LAG3 had significantly higher (*p < 0.05) T-cell proliferation than with the other clinical grade immune modulators, upon stimulation with the mixture of ten different MM cell lines, either as irradiated whole cells or tumor lysates." (PMID 34290359, 2022).